APP (amyloid beta precursor protein)
Diseases named in the same sentence as APP in open-access papers (continued):
Sharing a sentence is not in itself a finding about the gene and the disease.
Cognitive impairment (continued). "Random forest analysis suggests that Helicobacter and Mucispirillum show a significant difference among the groups, indicating that these bacteria were involved in the pathogenesis of AD, and TS prevents cognitive impairment in APP/PS1 mice by remodeling the GM." (PMID 35935875, 2022). "Theoretically and empirically, it might be related to the pathological processes of cognitive impairment and the specific characteristics of the APP/PS1 transgenic mouse model." (PMID 35281906, 2022). "Therefore, this study examined if and how RH participates in the progression of AD-type pathology and cognitive deficits in APP/PS1-DM mice." (PMID 35077394, 2022). "In vivo, we investigated whether OCYYoung‐EVs could ameliorate cognitive impairment and the pathogenesis of AD in early or later stages of APP/PS1 AD model mice." (PMID 35508803, 2022). "Consequently, this stimulation significantly reduced the expression of Aβ, APP, and pTau, which in turn not only recover the spatial learning and memory defects but alleviate the cognitive impairment of learning and memory in APP/PS1 mice." (PMID 36614120, 2022). "Older Tg APP/PS1 mice exhibit cognitive impairment that affects spatial learning and memory." (PMID 35917088, 2022). "Our previous studies also showed that L‐NBP improved cognitive impairment in an APP/PS1transgenic AD mouse model might through inhibitory effects of CDK‐5 and GSK‐3β signaling pathways." (PMID 35445545, 2022). "The excess accumulation of Aβ, which is attributed to the amyloidogenic cleavage of APP, is deemed to display a strong relevance with the pathology of AD, which may further result in neurotoxicity and cognitive impairment." (PMID 35156515, 2022). "Collectively, these data indicated that TS treatment could significantly alleviate cognitive impairment in APP/PS1 mice." (PMID 35935875, 2022). "Exercise alleviates AD-like lesions and cognitive impairment in APP/PS1 mice." (PMID 36077318, 2022). "APP/PS1 transgenic mouse model can be used to simulate cognitive impairment in AD." (PMID 35281906, 2022). "Evidence from a series of recent experiments revealed that AQP-4 is responsible for bulk ISF flow in the glymphatic system, and its deletion resulted in Aβ deposition, aggravation of cognitive impairment, and induction of cerebral amyloid angiopathy in APP/PS1 mice." (PMID 36551947, 2022). "In summary, LPD could increase brain glucose metabolism and ameliorate cognitive deficits through PPARγ-dependent enhancement of mitophagy in APP/PS1 mice." (PMID 36217155, 2022). "Consistent with most articles, our results showed that long-term voluntary running significantly alleviated cognitive impairment, increased hippocampal volume in the DG and CA1 regions, reduced hippocampal Aβ deposition, and prevented synaptic loss in APP/PS1 mice." (PMID 35123512, 2022). "In addition, chronic oral FA administration was shown to decrease cerebral Aβ deposition and mitigate cognitive impairment in APP/PS1 transgenic mice." (PMID 35052635, 2022). "Introduction of this PKCα mutation onto the B6;SJL background without the APP transgene (non tg-AD) did not cause cognitive impairment at either of the early ages tested, but deficits were apparent at 12 months of age." (PMID 36418293, 2022). "Hence, the present data suggest that meprin β contributes to the development of cognitive impairments in APP/lon mice." (PMID 35235058, 2022). "In order to determine whether the cMPT lesion and associated OSA phenotypes exacerbated the core features of AD (cognitive impairment, amyloid plaques, neuroinflammation, and neurodegeneration), we used the commonly studied APP/PS1 familial AD mouse model." (PMID 36323689, 2022). "Similarly, aFGF-stimulated astrocyte-derived EVs alleviated the brain Aβ burden and cognitive deficits in the APP/PS1 mice." (PMID 36559145, 2022).
Cognitive impairment (continued). "Recently, it has been shown that ovocystatin might prevent aging-related cognitive impairment in rats and reduce memory decline in an APP/PS1 mice model." (PMID 35566501, 2022). "Both the MWM and SDPA test indicated that VAD could aggravate the learning and memory impairment, thus exacerbating the cognitive deficits in the APP/PS1 transgenic mice." (PMID 34790112, 2021). "Recently, Sun showed that treatment with Clostridium butyricum, a SCFA butyrate producer, could prevent cognitive impairment, Aβ deposits, microglia activation, and production of tumor necrosis factor‐α and interleukin‐1β in the brain of APP/PS1 mice." (PMID 32929861, 2021). "The transgenic mice expressing human APP/PSEN1-Tg carrying familial AD mutations used in these studies (B6C3-Tg) have an onset of plaque pathology at around 6 months, which is followed by cognitive impairments with both increasing by 12–18 months of age." (PMID 33795014, 2021). "The SZRD, especially the L-SZRD, may improve the cognitive impairment and ameliorate the neural degeneration in APP/PS1 transgenic mice through inhibiting Aβ accumulation and neuroinflammation via the JAK2/STAT3 pathway." (PMID 33478552, 2021). "Moreover, miR-181a was previously reported to protect against pericyte apoptosis for ameliorating cognitive deficits in APP/PS1 mice." (PMID 34594577, 2021). "It is well known that APP/PS1 develops cognitive impairment in mice aged 9 months." (PMID 34658785, 2021). "We first assessed the preventive effects of MN‐08 on cognitive impairment in APP/PS1 mice." (PMID 33955647, 2021). "However, there is still a lack of a systematic research on the effects of TSA in ameliorating cognitive deficits and pathological damage of APP/PS1 mice." (PMID 33397436, 2021). "Indeed, inhibiting IL-12/IL-23 signaling either by the administration of an IL-12p40–neutralizing antibody or genetic ablation of IL-12/IL-23 subunits ameliorates Aβ pathology and cognitive impairment in APP/PS1 mice." (PMID 33847763, 2021). "In addition, supplementation with a choline diet during pregnancy effectively ameliorates the cognitive impairment of APP/PS1 mice and their progeny and improves their memory." (PMID 33819195, 2021). "A number of reports from different scientific groups demonstrated the change of APP ratio during the progression of AD and several studies have shown that APP ratio was decreased in patients with mild cognitive impairment (MCI) compared to the healthy elderly individuals." (PMID 34440494, 2021). "Acetate is a kind of SCFA with neuroprotective activity and could significantly improve the cognitive impairment of APP/PS1 mice." (PMID 33584734, 2021). "Environmental stress may activate the APP/PS1 gene, which may further cause cognitive deficits and an impaired neuroinflammatory response to amyloid pathology." (PMID 33407614, 2021). "The latest study found that SBP might ameliorate the cognitive impairment in APP/PS1 transgenic mice via inhibition of Aβ fibril formation and suppression of secretions of cytokines." (PMID 33986688, 2021). "Of note, we recently found that APP Tyr682 phosphorylation increases in fibroblasts of AD patients, opening up to the possibility to use APP Tyr682 phosphorylation level as a potential powerful tool in detecting early signs of AD-related cognitive disorders in peripheral cells." (PMID 34572510, 2021). "In summary, our results identified that agomelatine could improve cognitive impairment and ameliorate AD-like pathology in APP/PS1 mice via activating DHCR24 signaling and inhibiting Akt/mTOR and Hes1/Notch1 signaling pathway." (PMID 35153715, 2021). "Accordingly, there was cognitive impairment in APP/PS1 mice with sevoflurane exposure." (PMID 32385796, 2021). "Therefore, to identify potential long-term impacts of H3N2 IAV infection on the progression of cognitive impairments in APP/PS1 mice, learning and memory formation were assessed using the Morris water maze (MWM) paradigm." (PMID 33994946, 2021).
Cognitive impairment (continued). "DLT as a 5HT2AR antagonist effectively improved cognitive impairment of APP/PS1 mice." (PMID 33369003, 2021). "However, a common element between various major psychiatric diseases appears to be the altered metabolism of APP, and the role of amyloid and tau as a biomarker of cognitive impairment." (PMID 34679416, 2021). "Memantine may improve the cognitive impairment of APP/PS1 mice through enhancing this EC–CA1 pathway." (PMID 34120588, 2021). "Interestingly, overexpression of SNX8 reduces Aβ levels and rescues cognitive impairment in an APP/PS1 AD mouse model." (PMID 34524084, 2021). "Inhibition of ERK by thiacremonone attenuates cognitive impairments in APP/PS1 transgenic mice." (PMID 34403210, 2021). "In addition, they have been successfully used to detect early cognitive deficits starting at 3 moa in APP/PS1-21 mice, suggesting higher sensitivity than the DAT." (PMID 34054444, 2021). "AD pathological phenotype might accelerate metabolic changes and cognitive impairment in APP/PS1 mice treated with HFD." (PMID 33291072, 2020). "Collectively, these studies demonstrate that overexpression of δ-secretase elicits both APP and Tau cleavage and leads to AD-like pathologies and cognitive impairments in hAPP/hMAPT double-transgenic mice regardless of APP or Tau mutation." (PMID 33311478, 2020). "PL402 ameliorates cognitive deficits and improves memory retention in APP/PS1 mice." (PMID 31901901, 2020). "Thus, novel object recognition and Morris water maze tests indicated that GLT-1 knockdown inhibited the improvement of Cef on cognitive impairment in APP/PS1 AD mice." (PMID 33132901, 2020). "To determine whether AS86 attenuated cognitive impairment in APP/PS1 mice by synaptic repair, we examined the presynaptic marker protein synaptophysin in CA1 area of hippocampus." (PMID 32550908, 2020). "Importantly, the behavioral tests by Morris Water maze indicated that SBP attenuated cognitive impairments in APP/PS1 transgenic mice." (PMID 32765267, 2020). "Our data suggests that APP overexpression in the J20 mouse causes cognitive deficits through inflammation, rather than Aβ deposition." (PMID 32917871, 2020). "Genetic predisposition for developing AD might accelerate metabolic changes and cognitive impairment in APP/PS1 mice treated with HFD." (PMID 33291072, 2020). "A previous study indicates that APP/PS1 mutation-induced brain injury and cognitive impairment may be caused by changes in neuronal activity." (PMID 33088260, 2020). "The overexpression of C/EBPβ in an AD mouse model accelerates the onset of AD-like pathogenesis and worsens cognitive dysfunctions, while a reduction in C/EBPβ expression decreases the expression of δ-secretase, APP and tau and reverses both amyloid and tau pathology and cognitive impairments." (PMID 31911834, 2020). "Following these findings, we aimed to test whether hyperexcitable PV interneurons are directly responsible for early cognitive impairment in APP/PS1 mice." (PMID 31431685, 2020). "In summary, this study provides essential preclinical evidence suggesting that EA reverses cognitive deficits and substantially lowers the burden of APP in AD model APP/PS1 mice, at least partially by inhibiting the JNK signaling pathway and regulating apoptosis signals." (PMID 32116652, 2020). "In addition to the previous studies, SBP improved the cognitive impairment of APP/PS1 transgenic mice possibly through neuroprotection, enhancement of cholinergic signal transmission and promote neurogenesis." (PMID 32765267, 2020). "The potential effect of SBPEtOH extract in attenuating the cognitive impairments in APP/PS1 transgenic mice was shown by following lines of evidence: (i) inhibition of Aβ fibril formation, (ii) suppression of secretions of cytokines, and (iii) improvement of behavioral tests by Morris water maze." (PMID 32765267, 2020).
Cognitive impairment (continued). "Taken together, the NgR reduction could improve the short-term and long-term memory functions and rescue the cognitive deficits in APP/PS1 transgenic mice." (PMID 32331528, 2020). "Moreover, APP/PS1 transgenic mouse exhibits cognitive impairments, and which can be examined by behavioral assays." (PMID 32765267, 2020). "We reversed the downregulation of miR-338-5p in the brain of APP/PS1 mice aged 8-month-old and 10-month-old through intrahippocampal injection of lentiviral vector overexpressing miR-338-5p to test whether miR-338-5p affects cognitive deficits in APP/PS1 mice." (PMID 33087587, 2020). "Here, we describe the potential therapeutic benefit of an AAV-form of the CBD3 peptide in amelioration of cognitive impairment, reduction of neuronal apoptosis, and normalization of the exaggerated levels of AD-related proteins, such as Aβ1–42, p-tau, and t-tau using the APP/PS1 mouse model." (PMID 32272942, 2020). "Last, SBP improved cognitive impairment of APP/PS1 transgenic mice." (PMID 32765267, 2020). "While the pathological outcome of APP dysregulation is mainly associated to its overexpression, recent studies showed that APP expression levels tend to decrease with age, and APP-knockout mice show age-dependent cognitive deficit and impaired locomotor activity." (PMID 33228083, 2020). "Abnormal APP processing could generate Aβ, which plays a pivotal role in the pathogenesis of cognitive disorders." (PMID 32714134, 2020). "High Aβ antibody titers induced by Y-5A15 vaccine attenuated cognitive impairment in APP/PS1 mice." (PMID 32630299, 2020). "All these findings suggested that BACE1 could be a disease-modifying therapeutic target to ameliorate cognitive impairments and alleviate multipathogenesis of APP/PS1 mice." (PMID 31223308, 2019). "Therefore, the APP/PS1 model of transgenic mice is valuable for modeling cognitive impairment in AD." (PMID 31248209, 2019). "This is in line with other tauopathies, where APP and Aβ deposition does not mirror p-tau deposition and is more likely associated with subject age than degree of cognitive impairment." (PMID 31831066, 2019). "Therefore, even if 6-month old APP/PS1 mice already expressed cognitive impairment, the Y-maze test reveals in APP/PS1 mice with NAFLD even lower spontaneous alternations." (PMID 31130652, 2019). "We showed that oral administration of plant GlcCer to APP transgenic mice markedly reduced Aβ levels and amyloid plaques and eventually attenuated Aβ-related pathologies, such as inflammation, synaptic dysfunction and cognitive deficits." (PMID 31727994, 2019). "Low-dose ZGM1 significantly rescued cognitive impairment in APP/PS1 mice." (PMID 31847879, 2019). "Additionally, marginal vitamin A deficiency (MVAD) that has also been correlated with cognitive decline in the elderly, led to enhanced Aβ synthesis, plaque formation, and cognitive deficits in APP/PS1 mice." (PMID 31396076, 2019). "However, the M group showed worse acquisition performance over all training sessions, suggesting that the APP/PS1 dementia mice had obvious cognitive deficits." (PMID 31223308, 2019). "Tg‐APP/PS1 mice at 7.5 months of age display severe cognitive deficits." (PMID 30746828, 2019). "Our data also indicate that introduction of the Swedish mutation alone in endogenous APP is not sufficient to produce either AD-related brain pathology or cognitive deficits in mice." (PMID 30894120, 2019). "To evaluate the effects of DISC1‐mediated mitophagy in cognition, we therapeutically express DISC1 in the hippocampus of APP/PS1 transgenic mice at 8 months old of age, when these mice harbor extensive Aβ plaques and loss of synapses, exhibiting cognitive deficits." (PMID 30488644, 2019). "Given that prolonged SNX8 overexpression can ameliorate cognitive impairment at late stages in APP/PS1 mice, it seems likely that restoration of SNX8 function at early stages of AD onset may confer protective effects during advanced stages of disease onset." (PMID 31551717, 2019).
Cognitive impairment (continued). "Furthermore, upregulation of MKP-1 reduced Aβ production and plaque formation and improved hippocampal long-term potentiation (LTP) and cognitive deficits in APP/PS1 transgenic mice." (PMID 31840000, 2019). "All these facts contributed to a significant reduction of cognitive impairment in APP/PS1 mice." (PMID 30876953, 2019). "So far, our results indicate that reductions in SNX8 levels in human AD and mouse APP/PS1 AD models may potentially enhance amyloidogenic APP processing to promote Aβ accumulation and cognitive impairment." (PMID 31551717, 2019). "For example, APP-SwDI transgenic mice overexpressing human APP bearing three distinct FAD mutations demonstrate significantly enhanced Aβ production, plaque deposits, and cognitive impairments." (PMID 31306446, 2019). "NLRP3 gene deletion had protective effects on cognitive impairment in APP/PS1 transgenic mice." (PMID 31461911, 2019). "In the present study, we investigated whether hyperoxygenation treatment changes the Aβ‐induced pathology and cognitive impairment seen in Tg‐APP/PS1 mice." (PMID 30746828, 2019). "Taken together, our findings in this study suggested that NPS could ameliorate cognitive deficits, strengthen synaptic structure and function by promoting synaptic plasticity and reduce Aβ deposition in APP/PS1 transgenic mice." (PMID 31293402, 2019). "The results of the MWM test demonstrated that repeated EA treatment could improve the cognitive deficits in APP/PS1 mice." (PMID 31223308, 2019). "This suggests that SNX8 overexpression may attenuate amyloidogenic APP processing and cognitive deficits." (PMID 31551717, 2019). "EA treatment alleviated cognitive impairments in APP/PS1 mice." (PMID 31223308, 2019). "The first cognitive deficits have been reported to arise in APP/PS1 mice after approximately 6 months of age and we therefore addressed whether ES would have aggravated cognitive performance at 9 months, when the deficits should have been firmly established." (PMID 29563870, 2018). "Laboratory studies indicated that in APP/PS1 mouse models of AD, the genetic overexpression of apoA-I prevented the development of cognitive impairment, whereas the deficiency of apoA-I exacerbated cognitive impairments." (PMID 28824418, 2017). "Furthermore, in the water maze test, Y maze, and fear conditioning test, 5-HT6 antagonist SB271046 recovered the cognitive impairment of APP/PS1 mice." (PMID 28931427, 2017). "β-Site amyloid precursor protein (APP) cleaving enzyme 1 (β-secretase, BACE1) is a critical enzyme catalyzing amyloid β (Aβ) peptide generation by cleaving APP, and BACE1 activation is a hallmark of early stage cognitive deficits and plays an important role in progressive conversion to AD." (PMID 28851397, 2017). "Intraneuronal APP/Aβ may be the major culprit in the early-onset network hyperexcitability in AD which may ultimately contribute to cognitive impairment." (PMID 28392767, 2017). "The present results indicated that BJJS could attenuate cognitive impairment via ameliorating the AD-related pathological alterations in APP/PS1 mice." (PMID 29190943, 2017).